FGF21 (fibroblast growth factor 21)
Diseases named in the same sentence as FGF21 in open-access papers (continued):
Sharing a sentence is not in itself a finding about the gene and the disease.
metabolic disease (continued). "However, adipose- and cardiac muscle-sourced FGF21 require further attention to delineate their paracrine and/or autocrine roles in metabolic diseases." (PMID 35983184, 2022). "Since FGF21 corrects multiple metabolic disorders by improving lipid metabolism and body weight, one would expect rather low blood levels of FGF21 during metabolic disease progression." (PMID 36034414, 2022). "Thus, our results indicate that wogonin would be a strong candidate for a therapeutic to improve metabolic diseases by enhancing hepatic FGF21 production." (PMID 36235573, 2022). "In the past few decades, a considerable amount of interest has been generated in exploiting inter-organ signaling pathways, particularly organ-specific endocrine factors such as adipose-derived adiponectin, and liver-derived fibroblast growth factor 21, to treat metabolic disorders." (PMID 35557517, 2022). "Pharmaceutical development of FGF21-based drugs for metabolic diseases." (PMID 36618930, 2022). "As the liver is the main organ to secrete FGF21, wogonin might be a therapeutic that can ameliorate metabolic disorders." (PMID 36235573, 2022). "A refined understanding of the mechanisms that control FGF21 release in humans may accelerate the development of small-molecule FGF21 secretagogues to treat metabolic disease." (PMID 35111398, 2022). "Furthermore, some companies, such as Eli Lilly and Pfizer, have now developed FGF21 analogs and demonstrated their therapeutic potential in clinical trials for the treatment of metabolic diseases." (PMID 34703671, 2021). "GDF15, a divergent member of the transforming growth factor β superfamily, is an emerging biomarker comparable to FGF21, as its circulating levels are noticeably increased in various disease conditions including cancer, metabolic diseases, and aging-related disorders, as well as MetS." (PMID 33668309, 2021). "Taken together, these studies suggest that FGF21 may play a role in glucose and lipid metabolism, resulting in the improvement of the metabolic diseases." (PMID 33498410, 2021). "Pharmacological strategies to modulate the effects of FGF21 on related metabolic diseases." (PMID 33869312, 2021). "Consequently, some targeting FGF21 analogs have been developed for the treatment of metabolic disorders." (PMID 34675822, 2021). "As metabolic disorders are also risk factors for CKD, they may contribute to the elevation of FGF21 levels in patients with CKD." (PMID 34918690, 2021). "Fibroblast growth factor 21 (FGF21) is produced by tissues involved in metabolism, such as the liver, adipose tissues, skeletal muscle, and pancreas, and has been suggested to improve metabolic diseases and induce weight loss in humans and mice." (PMID 33588950, 2021). "Therefore, it can be summarized that exercise-mediated FGF21 production is different in metabolic diseases." (PMID 33498410, 2021). "FGF21 has been developed as a drug for the treatment of metabolic diseases." (PMID 33588950, 2021). "Paradoxically, FGF21 levels are elevated in metabolic diseases." (PMID 34141520, 2021). "Although the metabolic disorder in CKD is usually thought to be the cause of the elevated FGF21, its precise mechanism has not been illustrated so far." (PMID 34675822, 2021). "Finally, the role of FGF21 in the pathophysiology of metabolic diseases is supported by our genetic analyses providing evidence for a link between genetic variation within FGF21 and metabolic traits, in particular those related to lipid metabolism." (PMID 33805553, 2021). "It has been observed that the level of FGF21 fluctuates with different metabolic disorders." (PMID 34572066, 2021). "Based on these results, they suggested that FGF21 may be an effective novel biomarker for the diagnosis of metabolic disorders." (PMID 33498410, 2021). "All evidence suggests that FGF21 is a promising cytokine for the treatment of metabolic disorders." (PMID 33588950, 2021).
metabolic disease (continued). "The fusion of GLP-1 with FGF21 was motivated by their complementary pharmacology, thereby addressing the three criteria for an ideal combination therapy to treat metabolic disease: improved glucose metabolism, decreased food intake, and enhanced energy expenditure." (PMID 32923621, 2020). "FGF21 is induced by stress and serum levels correlate with various metabolic diseases." (PMID 33224151, 2020). "Moreover, FGF21 is strongly induced in animal and human subjects with metabolic diseases, is expressed predominantly in the liver, and has recently emerged as a promising drug candidate for NASH50,51." (PMID 33177546, 2020). "In contrast to FGF21 however, metabolic diseases exhibit reduced serum FGF19 levels." (PMID 33204460, 2020). "In efforts to develop new approaches in the fight against metabolic disorders, the discovery of metabolic hormones such as irisin and FGF21 and their potential to induce the browning of WAT, especially SAT, and the thermogenic capacity of BAT has gained great interest." (PMID 32040532, 2020). "With in-depth investigation, it has been demonstrated that FGF21 could modulate the activity of proliferator-activated nuclear receptor δ (PPAR-δ), so FGF21 is considered as a crucial PPAR-δ agonist which ameliorates metabolic disorders." (PMID 33213461, 2020). "The role of FGF21 as a therapeutic option in human metabolic diseases is of increasing importance." (PMID 30804796, 2019). "Recombinant FGF21 has been used for metabolic disease therapy in human." (PMID 30842736, 2019). "FGF21 has been shown to have numerous beneficial effects in ameliorating metabolic disorders." (PMID 31370146, 2019). "Therefore, the development of better recombinant FGF21 analogs as a potential treatment for metabolic diseases in humans is necessary." (PMID 30804796, 2019). "Regardless, an increase in the plasma level of FGF21 may serve as a potential biomarker for early-stage metabolic disorders." (PMID 31121855, 2019). "In the same way, it has been described that FGF21 does not appear to be the major mechanism through which PUFA ameliorates high-fat diet (HFD)-associated metabolic disorders." (PMID 31546675, 2019). "Thus, it has been suggested that the increases in FGF21 that parallel aging are related to the appearance of an age‐related FGF21‐resistant state, as has been proposed in metabolic diseases (Salminen, Kaarniranta, & Kauppinen, 2017)." (PMID 30043445, 2018). "Thus, our study indicates that activation of ER stress is the key event responsible for upregulation of FGF21 in several metabolic diseases." (PMID 29854743, 2018). "Notably, increased FGF21 expression was required for the effects of CO on metabolic disease during HFD feeding in vivo." (PMID 29295856, 2018). "FGF21 is involved in the pathogenesis of cardiovascular diseases and metabolic disorders." (PMID 28821258, 2017). "However, there have been no reports investigating the effect of exercise type (aerobic and resistance exercise) and intensity (vigorous and moderate intensity) on FGF-21 and irisin in metabolic diseases." (PMID 29036766, 2017). "Fibroblast growth factor 21 (FGF21), a hormone implicated in the regulation of glucose homoeostasis, insulin sensitivity, lipid metabolism and body weight, is considered to be a promising therapeutic target for the treatment of metabolic disorders." (PMID 26635356, 2016). "Since serum FGF21 increases in several kinds of CVDs, serum FGF21 levels might be regarded as a potential biomarker not only for diagnosis of metabolic disorders but also for diagnosis of CVD in clinics." (PMID 27247947, 2016). "Therefore, understanding the pathways and drugs that can modulate the FGF21 expression is of potential importance to human metabolic diseases." (PMID 27583452, 2016).
metabolic disease (continued). "In conclusion, to our knowledge, this is the first study demonstrating that smoking simultaneously increases two Klotho-related molecules; sαKl, capable of affecting anti-inflammatory cytokine network and FGF-21, a possible indicator of progressing metabolic disorder in men." (PMID 26382974, 2015). "Therefore, further studies to elucidate the physiological and pharmacological roles of FGF21 in detail are warranted so as to provide important insights for the use of FGF21 as therapeutic drugs to treat metabolic disorders." (PMID 26441837, 2015). "Finally, we provide data to justify continued investment into FGF21 pharmacology as the next generation therapeutic in the metabolic disease area." (PMID 26153793, 2015). "Multiple studies have shown the complexity of FGF21 in metabolic disease." (PMID 26092866, 2015). "FGF21 has generated interest as a potential therapeutic against metabolic disease." (PMID 25790234, 2015). "Moreover, our studies provide important information about the FGF21 signaling pathway and the clinical significance of FGF21 in the development of metabolic diseases." (PMID 24900988, 2014). "FGF21 has emerged as a promising therapeutic molecule for the treatment of metabolic diseases." (PMID 25365322, 2014). "Thus, we indicate ER stress is the key mechanism for regulating FGF21 in several metabolic diseases." (PMID 24900988, 2014). "Moreover, the elevated serum FGF21 level followed a positive incremental trend in conjunction with amount of metabolic disorders present in the patient." (PMID 23981342, 2013). "Increased level of serum FGF21 is associated with NAFLD, metabolic disorders and CAD." (PMID 23981342, 2013). "The attractiveness of FGF21 based preclinical pharmacology as a superior “glucose plus” agent has already inspired initial efforts to optimize and evaluate re-engineered FGF21 analogues in animal models of metabolic disease." (PMID 23823755, 2013). "Further study of FGF21 may provide clues as to its roles in lipid metabolism and clinical treatments for metabolic diseases." (PMID 21331285, 2011). "Fibroblast growth factor 21 (FGF21) is a promising drug candidate to combat metabolic diseases." (PMID 20163718, 2010). "Moreover, FGF21 is now a promising therapeutic target for metabolic diseases." (PMID 40005931, 2025). "Currently, FGF21 has been widely used in the prevention and rehabilitation of metabolic diseases such as hepatic lipid and glycolipid metabolism as well as cardiovascular diseases, and it may become one of the effective targets for metabolic disease prevention and rehabilitation." (PMID 38390325, 2024). "Indeed, pharmacological activation of FXR and FGF21 receptors has been demonstrated to enhance thermogenesis and WAT browning in animal models, and several FXR modulators and FGF21 analogues are currently under clinical evaluation for the treatment of metabolic diseases in humans." (PMID 39678347, 2024). "No clinical data are available to date regarding the possible role of FGF21 in OA prevention or progress; however, the proposed role of FGF21 agonists in treating liver steatosis and other metabolic diseases might be relevant for OA of metabolic origin or OA with disease comorbidities." (PMID 39683624, 2024). "In addition, FGF21 also re‐structured the gut microbiota profile and increased the relative abundance of Clostridiales, Ruminococcaceae, and Lachnospiraceae, thereby rescuing the PD‐induced metabolic disorders in the colon." (PMID 37334756, 2023). "However, the administration cycle of FGF-21 for metabolic diseases is often long." (PMID 37288111, 2023). "Therefore, we speculated that increased circulating FGF21 levels may be one marker of the compensatory ability of the renal outcomes to protect from adverse effects such as vascular and metabolic diseases." (PMID 37009852, 2023).
metabolic disease (continued). "In addition, wogonin, a Scutellaria baicalensis root extract and one of its components, could promote the expression of FGF21, thereby improving metabolic diseases." (PMID 37576954, 2023). "Furthermore, bariatric surgery seems to improve FGF21 sensitivity during high-fat diets by restoring Klb expression in WAT and downregulating hepatic FGF21 expression in streptozotocin-induced diabetic rats, further supporting a key role for FGF21 signalling in WAT during metabolic disease." (PMID 36034414, 2022). "Therefore, FGF21 might be a probable regulator to improve hepatocyte ability to oxidize lipids for ameliorating metabolic disorders in perinatal dairy cows." (PMID 35405926, 2022). "Upregulation of hepatic FGF21 expression may represent a way to treat metabolic diseases." (PMID 36045720, 2022). "Although both parameters (possibly GDF-15 superior to FGF-21) are considered capable of distinguishing patients with mitochondrial diseases from those without, serum concentrations of both molecules are likely to be significantly affected by vascular and metabolic diseases." (PMID 34572118, 2021). "Thus, we postulated that high FGF21 levels in our studied group were associated with a metabolic disorder, not induced by exercise." (PMID 33670024, 2021). "In addition, the FGF21 analog LY2405319 (LY) with the half-life improving exerts an inhibitory effect on blood sugar and lipids, which indicates that the FGF21 pathway may be an ideal candidate for the treatment of metabolic diseases." (PMID 34675822, 2021). "Furthermore, we present new results regarding the relationship between FGF21 and other adipocytokines that may uncover and help to understand complex pathways in the pathophysiology of metabolic diseases." (PMID 33805553, 2021). "Furthermore, the ability of pGSN to identify young MD patients warrants further research to confirm its potential utility in pediatric patient series, where GDF15 and FGF21 have been shown to be less relevant in differentiating multisystemic mitochondrial disorders from other metabolic diseases." (PMID 34203775, 2021). "It is unknown whether the observed changes in FGF21 following 2 weeks of high‐fructose consumption are sustained over months or years or whether these changes are predictive of or protective against the development of metabolic disease." (PMID 31687174, 2019). "However, the effects of FGF21 on impaired endothelial dysfunction of blood vessels in metabolic diseases remains unclear." (PMID 31511499, 2019). "It is not known whether or how these differences in baseline FGF21 levels affect risk for the development of metabolic disease later in life, with or without dietary manipulation." (PMID 31687174, 2019). "To date, literature on the physiology and regulation of FGF21 in humans indicates that this important regulatory protein acts as both a marker of metabolic disease and a hormone with anti‐inflammatory and protective effects against the development of metabolic disease." (PMID 31687174, 2019). "However, the precise role of upregulated FGF21 in metabolic disorders remains uncertain." (PMID 30127382, 2018). "Nevertheless, our findings that an increase of FGF21 by CO improves metabolic dysfunction suggest that a low-dose application of CO may represent a potential therapeutic strategy for the amelioration of metabolic diseases." (PMID 29295856, 2018). "In addition, circulating FGF-21 levels at baseline have been shown to predict the development of metabolic diseases in different populations, indicating that FGF-21 can also be used as a screening and diagnostic biomarker for metabolic diseases." (PMID 30298107, 2018). "Therefore, serum levels of FGF-21 might be a predictor of progressing metabolic disorder especially in male smokers." (PMID 26382974, 2015). "Dysregulation of FGF19 and/or FGF21 may contribute to the development of those metabolic diseases." (PMID 24260557, 2013).
metabolic disease (continued). "In the present study, NAFLD subjects were found to have higher level of serum FGF21 and those subjects with multiple metabolic disorders were found to have the highest level of serum FGF21, thereby supporting the hypothesis that this factor is involved in glycolipid metabolism." (PMID 23981342, 2013). "The lower level of FGF21 in the control group is most likely due to the lack of chronic liver diseases and is associated with metabolic disorders, inflammation, and oxidative stress, which are seen in patients before liver transplantation and may cause an increase in FGF21." (PMID 39941067, 2025). "Growth differentiation factor 15 (GDF15) and fibroblast growth factor 21 (FGF21) are stress-induced cytokines increased in age-related and metabolic disorders." (PMID 40828431, 2025). "A large, long-term, well-designed RCT or a multicenter collaborative RCT is warranted to provide deeper insights into the clinical benefits of FGF21 analogs on glycemic parameters, lipid profiles, and circulating ADP levels in different metabolic disorders." (PMID 40756666, 2025). "Recent studies have confirmed that FGF21 may become one of the effective targets for the prevention and rehabilitation of metabolic diseases, and is widely used in the prevention and rehabilitation of metabolic diseases such as liver lipid, glucose and lipid metabolism." (PMID 39296716, 2024). "Meanwhile, pharmaceutical companies have designed and tested a multitude of FGF19- and FGF21-mimetics, recognizing KLB as a promising drug target for treating various metabolic diseases in humans." (PMID 37260446, 2023). "Recently, we uncovered a key role for fibroblast growth factor 21 (FGF21), a promising drug target for treatment of metabolic disease, in this phenomenon." (PMID 37355753, 2023). "Through the development of FGF19- and FGF21 mimetics, KLB has emerged as a promising drug target for treating various metabolic diseases, such as type 2 diabetes (T2D), non-alcoholic fatty liver disease (NAFLD), and cardiovascular disease." (PMID 37260446, 2023). "Paradoxically, serum FGF21 in T2DM patients with HP was significantly higher than in control, which seems to contradict that the FGF21 can improve metabolic disorders." (PMID 37424900, 2023). "The recognition of KLB as an exciting drug target for a variety of common metabolic diseases encouraged many pharmaceutical companies to develop a multitude of FGF19 and FGF21 analogs." (PMID 37260446, 2023). "The changes in FGF21 level in different populations showed the protective function of FGF21 on the circulatory system, such drugs targeting FGF21 for treating CVD and metabolic diseases will be an excellent boon for cardiovascular patients." (PMID 37424900, 2023). "The fibroblast growth factor 21 (FGF21) gene plays an important role in the mechanism of glucose and lipid metabolism and is a promising therapeutic target for metabolic disease." (PMID 37505857, 2023). "Since FGF-21 was first identified in mouse embryos in 2000, an increasing number of studies have shown a positive relationship between FGF-21 and various metabolic diseases in humans." (PMID 37658393, 2023). "Simultaneously, FGF-21 analogs and FGF-21 receptor agonists show promise as a treatment approach for aging-related metabolic diseases." (PMID 37259294, 2023). "Because FGF21 provides a downstream mechanism contributing to several metabolic interventions, and given its direct clinical importance, these findings may have broad implications for the targeted application of nutritional and pharmacological treatments for metabolic disease." (PMID 35998055, 2022). "AhR can also regulate fibroblast growth factor 21 (FGF21), which protects properties against metabolic disease by promoting energy expenditure and improving both lipid and glucose metabolism." (PMID 35887027, 2022).